CNKSR2 (connector enhancer of kinase suppressor of Ras 2)
Description:
May function as an adapter protein or regulator of Ras signaling pathways.
Synonyms: CNK2; KIAA0902; KSR2; MAGUIN; MRXSHG
Tractability: Antibody: its Gene Ontology location is reachable by antibodies, with high confidence; UniProt places it where antibodies can reach, with medium confidence; the Human Protein Atlas places it where antibodies can reach. PROTAC: its protein half-life has been measured.
Gene: Protein-coding gene on chromosome X (21,372,801 to 21,654,695, forward strand). Ensembl gene ENSG00000149970.
Subcellular location: Cytoplasm; Membrane
Subcellular location (Human Protein Atlas): Golgi apparatus; Plasma membrane
Pathways (Reactome):
Disease: Paradoxical activation of RAF signaling by kinase inactive BRAF; Signaling by BRAF and RAF1 fusions; Signaling by RAF1 mutants; Signaling by high-kinase activity BRAF mutants; Signaling by moderate kinase activity BRAF mutants; Signaling downstream of RAS mutants
Signal Transduction: MAP2K and MAPK activation
Gene Ontology:
Molecular function: protein binding; protein kinase binding; protein-macromolecule adaptor activity; identical protein binding
Biological process: intracellular signal transduction; enzyme-linked receptor protein signaling pathway; postsynaptic specialization organization; postsynapse organization; regulation of signal transduction
Cellular component: extracellular exosome; plasma membrane; glutamatergic synapse; cytoplasm; extrinsic component of postsynaptic density membrane; membrane; neuronal cell body; postsynaptic density; postsynaptic membrane
Gene-disease validity (ClinGen):
ClinGen rates the evidence that CNKSR2 causes each of these diseases.
X-linked complex neurodevelopmental disorder (X-linked): Definitive. A complex neurodevelopmental disorder that is transmitted via X-linked inheritance, and is characterized by intellectual disability, autism and epilepsy.
Homologues: Orthologues: chimpanzee CNKSR2 (100% identical), macaque CNKSR2 (99% identical), rabbit CNKSR2 (99% identical), dog CNKSR2 (99% identical), pig CNKSR2 (99% identical), rat Cnksr2 (99% identical), mouse Cnksr2 (99% identical), guinea pig CNKSR2 (90% identical), tropical clawed frog cnksr2 (82% identical), zebrafish cnksr2a (75% identical), zebrafish cnksr2b (65% identical), Drosophila melanogaster cnk (26% identical), and 1 more. Paralogues in human: CNKSR3 (30% identical), CNKSR1 (23% identical), IPCEF1 (16% identical), SAMD3 (11% identical).
Diseases named in the same sentence as CNKSR2 in open-access papers:
CNKSR2 is named in the same sentence as 58 diseases in open-access papers, as found by Europe PMC text mining. Sharing a sentence is not in itself a finding about the gene and the disease. The quoted sentences say what the papers report.
Intellectual disability (11 papers, 2019 to 2025). "According to clinical manifestations, genetic pattern and ACMG classification of mutation site as Class 1-cause disease, the patient was diagnosed as Houge type of X-linked syndromic mental retardation caused by CNKSR2 gene mutation." (PMID 34114993, 2021). "Mutations of connector enhancer of kinase suppressor of Ras-2 (CNKSR2) gene were identified as the cause of Houge type of X-linked syndromic mental retardation." (PMID 34114993, 2021). "This study enhances our knowledge of the CNKSR2 gene mutation spectrum and provides further information about the phenotypic characteristics of X-linked syndromic intellectual disability." (PMID 32245427, 2020). "Eight different deletions and point variants of the X‐chromosomal gene CNKSR2 have been reported in families with males presenting intellectual disability (ID) and epilepsy." (PMID 31414730, 2019). "However, some females heterozygous for a CNKSR2 pathogenic variant have intellectual disability and seizures." (PMID 34266427, 2021). "Cnksr2 has been identified in genome-wide association studies as an ASD candidate, and mutations in this gene have been shown to cause epilepsy and intellectual disability." (PMID 34939924, 2021). "CNKSR2 is now considered as a causative gene of the Houge type of X-linked syndromic mental retardation (MRXHG), an X-linked Intellectual Disability (XLID) that exhibits delayed development, intellectual disability, early-onset seizures, language delay, attention deficit, and hyperactivity." (PMID 35053419, 2022).
epilepsy (8 papers, 2018 to 2026). A brain disorder characterized by episodes of abnormally increased neuronal discharge resulting in transient episodes of sensory or motor neurological dysfunction, or psychic dysfunction. "Partial deletion and deficiency of MAGUIN/CNKSR2 and point mutations in MAGUIN/CNKSR2 are involved in nonsyndromic X-linked intellectual disability accompanied with epilepsy and aphasia and MAGUIN/CNKSR2 is associated with schizophrenia." (PMID 36803960, 2023). "We speculate that variants removing only the C terminal of CNKSR2 may result in brain expression of a truncated protein with most domains present, which can cause the novel CNKSR2‐related features as well as in neurological features such as ID, language and motor delay, and epilepsy, in females." (PMID 31414730, 2019). "Hence CNKSR2 gene has a role to play in ESESS/CSWSS/epilepsy-aphasia spectrum." (PMID 29976148, 2018). "Therefore, epilepsy in the human patients with mutations in MAGUIN/CNKSR2 may not be simply caused by the defects in the excitatory synaptic transmission." (PMID 36803960, 2023). "Among the triplosensitive genes located in the duplicated region, ARX, CDKL5, CNKSR2, MID1, PTCHD1, RPS6KA3, and SMS are known to be involved in intellectual developmental disorders with/without epilepsy." (PMID 39062680, 2024).
X-linked intellectual disability (5 papers, 2020 to 2024). An X-linked intellectual deficiency in which not enough information is known, reported or published to indicate whether a gene causes non-syndromic or syndromic presentations. "CNKSR2 is associated with different hereditary diseases, including nonsyndromic X-linked intellectual disability, mental retardation and undetermined early-onset epileptic encephalopathy." (PMID 38169557, 2024). "Clinically, the partial deletion or deficiency of MAGUIN/CNKSR2 can be a cause of nonsyndromic X-linked intellectual disability and seizure." (PMID 36803960, 2023). "The scaffold protein connector enhancer of kinase suppressor of Ras 2 (CNK2) is predominantly expressed in neural tissues and was recently implicated in X-linked intellectual disability (ID)." (PMID 32235845, 2020).
developmental delay (4 papers, 2021 to 2025). "These two boys both had mental retardation, developmental delay, and early-onset epilepsy, consistent with past reports of pathogenic variants in CNKSR2." (PMID 39920708, 2025). "Pathogenic variants in connector enhancer of kinase suppressor of Ras-2 (CNKSR2) located on the X chromosome (Xp22.12) lead to a disorder characterized by developmental delay and a characteristic seizure phenotype." (PMID 34266427, 2021). "This may have affected the protein level of CNKSR2 and was related to the developmental delay of our patients." (PMID 38337158, 2024).
Aphasia (3 papers, 2018 to 2024). An acquired language impairment of some or all of the abilities to produce or comprehend speech and to read or write. "In conclusion, this study provides evidence that aphasia and seizures are governed by glutamatergic and GABAergic neurons, respectively, in the Cnksr2 model of EAS." (PMID 39694826, 2024). "Recent studies have implicated heterozygous loss-of-function mutations of CNKSR2 with EAS, which are characterized by seizures, aphasia or the progressive loss of language, attention deficits, and X-linked neurodevelopmental disorders." (PMID 39694826, 2024).
breast carcinoma (3 papers, 2014 to 2024). "In our study, we report for the first time that Smurf2 knockdown caused a marked decrease in the expression of CNKSR2 which in turn downregulates the proliferation and invasiveness properties of breast cancer cells via the PI3K-AKT signaling cascade." (PMID 25191523, 2014). "Previous studies have demonstrated that CNKSR2 plays a role in some diseases, including breast cancer and thyroid carcinoma 19,20." (PMID 38169557, 2024). "We reported previously that transient inhibition of Smurf2 expression decreased the proliferative potential of breast cancer cells by modulating CNKSR2 mediated PI3K-AKT signaling csascade." (PMID 29534682, 2018). "The present study provides the first evidence that silencing Smurf2 using synthetic siRNAs can regulate the tumorigenic properties of human breast cancer cells in a CNKSR2 dependent manner." (PMID 25191523, 2014). "Altogether, our findings reveal that Smurf2 is a novel positive regulator of CNKSR2 and suggest that Smurf2-CNKSR2 interaction may serve as a common strategy to control proliferation of human breast cancer cells by modulating CNKSR2 protein stability." (PMID 29534682, 2018). "The aim of this study was to investigate whether the interaction between Smurf2 and CNKSR2 has any significant role in the post transcriptional regulation of CNKSR2 expression in breast cancer." (PMID 29534682, 2018). "Indeed, we observed that knockdown of Smurf2 downregulated the expression of CNKSR2 and reduced the proliferative potential of human breast cancer cells." (PMID 29534682, 2018). "Furthermore, we demonstrated that silencing of Smurf2 downregulated the proliferation of breast cancer cells by modulating the PI3K- PTEN-AKT-FoxO3a pathway via the scaffold protein CNKSR2 which is involved in RAS-dependent signaling pathways." (PMID 25191523, 2014). "In summary, studies from our laboratory have shown that silencing of Smurf2 with siRNA resulted in significant inhibition of focus formation potential, anchorage-independent growth capability, migration, invasiveness, and proliferation in breast cancer cells by a possible interaction with CNKSR2." (PMID 25191523, 2014). "Thus Smurf2 knockdown probably downregulates proliferation of breast cancer cells in a CNKSR2 dependent manner by modulating the PI3K- PTEN-AKT-FoxO3a pathway." (PMID 25191523, 2014). "It will be important to determine whether Smurf2 can interact with CNKSR2 which possess a PPxY sequence in its structure which is necessary for interaction with WW domain of Smurf2 and whether its levels correlate with each other in human breast cancer progression models." (PMID 25191523, 2014). "Together, these data suggest that Smurf2 knockdown modulates the proliferation and invasiveness of breast cancer cells via regulating the PI3K-AKT signaling pathway and its downstream targets in a CNKSR2 dependent manner." (PMID 25191523, 2014). "Conversely, Smurf2 knockdown resulted in a marked decrease in the protein level expression of CNKSR2 by facilitating enhanced polyubiquitination and proteasomal degradation and reduced the proliferation and clonogenic survival of MDA-MB-231 breast cancer cell lines." (PMID 29534682, 2018). "Contrary to this speculation, it was consistently observed that CNKSR2 protein levels were decreased by siRNA mediated Smurf2 depletion in MDA-MB-231 and MCF7 breast cancer cell lines, SW480 colon cancer cell line and SCC131 oral cancer cell line." (PMID 25191523, 2014).
schizophrenia (3 papers, 2017 to 2023). A major psychotic disorder characterized by abnormalities in the perception or expression of reality. "All these genes are associated with psychiatric conditions, ranging from ID i.e., CNKSR2, CTNNB1, ANK3, CASK and ASD i.e., CTNND2, ANK3 to schizophrenia i.e., CNKSR2 (GWAS, PGC-SCZ 2014) and bipolar disorder ANK3." (PMID 28713243, 2017).
melanoma (2 papers, 2020 to 2023). A malignant, usually aggressive tumor composed of atypical, neoplastic melanocytes. "The six pan-cancer X-linked genes (ATRX, CNKSR2, DDX3X, KDM5C, KDM6A, and MAGEC3) were examined for their association with melanoma survival by comparing the survival of all patients with the expression of genes above (high) or below (low) median expression levels." (PMID 32731355, 2020).
age-related macular degeneration (1 paper, 2021). Age-related loss of vision in the central portion of the retina (macula), secondary to retinal degeneration. "Utilizing PhenGenI, the gene found to be associated with PXF in our GWAS analysis was KSR2 rs895471, and the connector enhancer of this gene (CNKSR2) was found to be associated with age-related macular degeneration." (PMID 34299682, 2021).
Alzheimer disease (1 paper, 2021). A progressive, neurodegenerative disease characterized by loss of function and death of nerve cells in several areas of the brain leading to loss of cognitive function such as memory and language. "Absent CNKSR2 causes intellectual, attention, and language deficits, which are consistent with the clinical manifestations of Alzheimer’s disease." (PMID 33525573, 2021).
Anxiety (1 paper, 2024). Intense feelings of nervousness, tension, or panic often arise in response to interpersonal stresses. "Cnksr2 KO mice have increased seizures, impaired learning and memory, increased levels of anxiety, and loss of ultrasonic vocalizations (USVs)." (PMID 39694826, 2024). "Here, we leverage conditional deletion of the X-linked Cnksr2 in a neuronal cell-type manner in male mice to demonstrate that anxiety and impaired USVs track with its loss from excitatory neurons." (PMID 39694826, 2024). "Deletion of Cnksr2 in glutamatergic neurons leads to elevated levels of anxiety and loss of ultrasonic vocalizations in adult male mice, while deletion in GABAergic neurons does not." (PMID 39694826, 2024). "Together, our results reveal Cnksr2-based mechanisms that underlie USV impairments that suggest communication impairments can be dissociated from seizures or anxiety." (PMID 39694826, 2024). "Interestingly, loss of Cnksr2 in excitatory neurons using either CaMKII-cre or EMX-cre resulted in elevated anxiety." (PMID 39694826, 2024). "Thus, the effects on time spent in the open arms of the maze suggested that deleting Cnksr2 in glutamatergic cells of the cortex and hippocampus leads to elevated anxiety." (PMID 39694826, 2024). "Importantly, the elevated anxiety phenotype that was cosegregated with the loss of Cnksr2 in cortical glutamatergic neurons did not localize to the ACC, supporting the notion that anxiety is not a primary cause of the impaired USVs in these mice." (PMID 39694826, 2024).
autism (1 paper, 2020). Persistent deficits in social interaction and communication and interaction as well as a markedly restricted repertoire of activity and interest as well as repetitive patterns of behavior. "When we expanded the dataset to include the entire 271 autism susceptibility genes that are expressed in the human amygdala, we found an additional five genes (PHF21A, RNABP17, ELP4, CNKSR2, and NAV2) with altered expression in individuals with ASD." (PMID 32460837, 2020).
breast tumor (1 paper, 2018). "Concomitantly, we observed that expression of Smurf2 and CNKSR2 was associated with stage of breast tumor progression, showing increased expression from normal, hyperplastic breast samples, and fibroadenoma to in situ carcinoma to invasive breast carcinoma." (PMID 29534682, 2018). "Altogether, the expression of Smurf2 and CNKSR2 displayed a statistically significant association with progressive grades of breast tumor samples as evidenced by Chi squared test." (PMID 29534682, 2018). "Despite the independent association between Smurf2 and CNKSR2 expression with progressive breast tumor stages, the expression pattern of Smurf2 and CNKSR2 showed a significant positive association (P < 0.001) between each other among non-malignant and malignant tumors." (PMID 29534682, 2018). "Similarly, CNKSR2 was also found to be overexpressed in 62.5% of malignant breast tumors compared to the adjacent normal breast tissues." (PMID 29534682, 2018). "Eventhough our descriptive analysis indicated a statistically significant association between Smurf2 and CNKSR2 with progressive breast tumor cases, we further analyzed the association between expression status of Smurf2 relative to CNKSR2 in non-malignant and malignant tumors." (PMID 29534682, 2018). "However, CNKSR2 does not exhibit a significant upregulation at the mRNA level in breast tumor samples compared to normal breast tissues, which indicate that expression status of Smurf2 and CNKSR2 is mainly associated at the protein level rather than at the mRNA level." (PMID 29534682, 2018).
cervical cancer (1 paper, 2024). A primary or metastatic malignant neoplasm involving the cervix. "We also explored the gene expression profile of high- and low-CNKSR2 expression in patients with cervical cancer." (PMID 38169557, 2024). "Our study confirmed that CNKSR2 participates in synaptic assembly, particularly in cervical cancer with high CNKSR2 expression in various infiltrating immune cells, and can be used as a good tool for the prognosis of cervical cancer patients." (PMID 38169557, 2024). "We performed an enrichment analysis to explore the CNKSR2 coexpression genes in cervical cancer progression." (PMID 38169557, 2024). "Furthermore, the cAMP signaling pathway and calcium signaling pathways, which were reported to play a role in cervical cancer, were also enriched in cervical cancer tissues with high CNKSR2 expression." (PMID 38169557, 2024). "Additionally, considering the infiltration of immune cells, cervical cancer patients with high CNKSR2 expression can increase the possibility of multiple immune cell infiltrations in the tumor environment." (PMID 38169557, 2024). "Interestingly, high CNKSR2 expression was a good predictor of the survival outcome in cervical cancer patients." (PMID 38169557, 2024). "Various immune cells infiltrated cervical cancer with high CNKSR2 expression." (PMID 38169557, 2024). "Thus, the pathogenesis and mechanism of CNKSR2 in cervical cancer warrant further exploration." (PMID 38169557, 2024). "Therefore, we infer that CNKSR2 may participate in the formation of synapses between immune cells in the process of tumor immunity, promoting the function of tumor immunity and improving the survival outcome of cervical cancer." (PMID 38169557, 2024). "Additionally, the effects of high CNKSR2 expression and increased numbers of NK cells, mast cells and T cells on synaptic formation between different immune cells and tumor immune escape in cervical cancer have not been studied, warranting further study." (PMID 38169557, 2024). "However, we only used bioinformatics algorithms to estimate the biological role of CNKSR2 in cervical cancer, and we could not directly observe the biological function of CNKSR2 in cervical cancer." (PMID 38169557, 2024).
cervical squamous cell carcinoma (1 paper, 2024). A squamous cell carcinoma arising from the cervical epithelium. "However, the molecular function of CNKSR2 in cervical squamous cell carcinoma (CESC) remains unknown." (PMID 38169557, 2024).
Fibroadenoma (1 paper, 2018). A benign tumor of the breast characterized by the presence of stromal and epithelial elements. "Most of the normal/hyperplasia (75.00%) and fibrocystic cases (57.14%) showed only a mild expression of CNKSR2, whereas the intensity of CNKSR2 expression increases with progression in tumor grade with 14.29% of fibroadenomas, 42.86% of DCIS and 52.73% of IDC’s showing intense expression of CNKSR2." (PMID 29534682, 2018).
progeria (1 paper, 2021). "In humans, mutations in Banf1 result in progeria, whereas single nucleotide polymorphisms in Cnksr2 are associated with human longevity." (PMID 34306034, 2021).